SMAD2 (SMAD family member 2)
Diseases named in the same sentence as SMAD2 in open-access papers (continued):
Sharing a sentence is not in itself a finding about the gene and the disease.
lung cancer (81 papers, 2010 to 2026). A malignant neoplasm involving the lung. "Chidamide, an HDAC1 inhibitor, prohibits TGFβ‐induced SMAD2 phosphorylation and attenuation of TGFβ‐induced loss of E‐cadherin expression, leading to the inhibition of migration in lung cancer cells." (PMID 39083441, 2025). "The enhanced expression of GRP78, Src, MAPK, and Smad2/3 seemed to be associated with hypoxia-induced EMT in lung cancer A549 cells." (PMID 32268506, 2020). "The protein levels of p-Smad2 was reduced in the CDP138-deficient lung cancer cells, whereas the level of total Smad2 remained constant." (PMID 28880265, 2017). "We postulate that the mutants of Smad2 in lung cancer A549 cells led to the loss of cross-talk between p130cas and Smad2-activation." (PMID 24959295, 2014). "Approximately 50% of pancreatic carcinomas, 20% of colon carcinomas, and 10% of lung cancers exhibit mutations in SMAD4, and mutations in SMAD2 have been found in ~7% of colorectal and lung cancers." (PMID 20565773, 2010). "RBM15 deficiency induced ferroptosis in lung cancer through altering TGF-β/Smad2 pathway." (PMID 40682199, 2025). "Mutations in Smad2 and Smad4 genes have been found in 5–10% of lung cancers." (PMID 26356817, 2015). "Mutations in Smad2 and Smad4 genes have been found in less than 10% of lung cancers." (PMID 26356817, 2015). "A novel long non‐coding RNA adjacent to SMAD3, named SMAD3‐associated long non‐coding RNA (SMASR), is downregulated by TGF‐β through SMAD2/3 in lung cancer cells." (PMID 39083441, 2025). "This research underscores capsaicin's potential as a cytotoxic and pro-apoptotic phytochemical that modulates TGFβ and SMAD2 gene expression, reinforcing its potential to treat lung cancer." (PMID 39347291, 2024). "In lung cancer, the actin-binding protein profilin-2 binds to and thereby prevents HDAC1′s access to the promoters of SMAD2 and SMAD3, which causes activation and promotes EMT and angiogenesis in lung cancer cells." (PMID 38279330, 2024). "Capsaicin treatment significantly reduced the expression of TGF-β/SMAD2 anti-apoptotic genes in lung cancer cells." (PMID 39347291, 2024). "This study explored the impact of capsaicin on lung cancer cell lines, particularly focusing on the TGFβ and SMAD2 signaling pathways." (PMID 39347291, 2024). "Here we examined the effects of altered SMAD2/3 in fibroblast migration and its impact on the desmoplastic stroma formation in lung cancer." (PMID 36572730, 2023). "In skin squamous cell carcinoma and non–small cell lung cancer cells, Smad2 suppresses, whereas Smad3 promotes cancer formation, malignant progression, and metastasis." (PMID 36549646, 2022). "Although Smad2 and Smad3 are independently recruited to often distinct genomic regions upon TGF-β stimulation in A549 lung cancer cells, the underlying mechanisms of the distinct Smad2 and Smad3 functions remain mostly unclear." (PMID 36549646, 2022). "MDM2 induces epithelial-mesenchymal transition by enhancing Snail expression or via activation of Smad2/3 signaling in breast and lung carcinomas." (PMID 35177036, 2022). "KDM4C inhibition reduces the expression of TGF-β2 and decreased the protein levels of p-Smad2 and p-Smad3 in lung cancer cells." (PMID 33558705, 2021). "EGCG can inhibit EMT in lung cancer cells through deacetylation of Smad2 and Smad3 and downregulation of phosphorylated Smad2 and Erk1/2." (PMID 34072700, 2021). "We identified JMJD3 as a strong enhancer of TGF-β signaling in Ras-activated lung cancer cells and showed that it induces syntenin to promote the activation of Smad2/3, thereby promoting tumorigenic TGF-β function in EMT and metastasis." (PMID 33637682, 2021). "miR-136 (miR-136-5p) inhibited mobility, invasiveness, and epithelial–mesenchymal transition in lung cancer cells by targeting Smad2 and Smad3." (PMID 34806748, 2021). "TGF-β enhanced the proliferation in lung cancer cell with miR-27a, but the effect was reversed by Smad2 or Smad4 overexpression." (PMID 34712379, 2021).
lung cancer (continued). "In lung cancer, the expression of SETDB1 is upregulated in cancer tissues and cooperates with SMAD2/3 to inhibit lung cancer metastasis." (PMID 32393761, 2020). "As a result, we found that CTI-82 significantly inhibited the phosphorylation of SMAD2/3 at selected concentrations in the human lung cancer A549 cells and the human keratinocyte HaCaT cells." (PMID 32605257, 2020). "A previous study has shown that PFN2 promotes the growth and metastasis of lung cancer by epigenetic regulation of Smad2 and Smad3." (PMID 33234737, 2020). "Previous studies have shown that PFN2 contributes to epithelial-mesenchymal transition (EMT) and regulates Smad2/3 expression in non–small-cell lung cancer." (PMID 33234737, 2020). "Subsequently, other TGF-β signaling components, e.g., TGF-β receptors and SMADs (SMAD2 and SMAD3), were found to be mutated in various cancers, including bladder, colon, breast, esophageal, stomach, brain, liver, and lung cancers." (PMID 31195692, 2019). "EGCG also inhibits TGF-β1-mediated EMT by suppressing the acetylation of Smad2 and Smad3 in human lung cancer cells." (PMID 31311401, 2019). "IGFBP3 up-regulation in lung cancer cells leads to increased MET expression via Smad2/3 activation and results in EGFR- and Met-TKI dual resistance." (PMID 30609749, 2019). "Public data from Gene Expression Omnibus (GSE19188) showed that SMAD2 mRNA expression was significantly upregulated in lung carcinoma compared with that in normal lung tissues." (PMID 31762811, 2019). "Upregulation of TGF-β1 and SMAD2/3/4, increased SMAD2/3 phosphorylation and a loss of BAMBI expression were prominent in the lung cancer cell lines A549 and H1975." (PMID 29799477, 2018). "The results suggest that CUG2 and TGF-β synergistically induce the EMT by cooperation of Sp1 and Smad2/3, leading to metastasis of lung cancer cells." (PMID 27974707, 2017). "Collectively, these results indicate that celecoxib and sulindac antagonize the activation of MMP-9 and the phosphorylation of Smad2/3 promoted during TGF-β1-induced EMT in lung cancer." (PMID 27528025, 2016). "It has been reported that miR-10a silencing reverses cisplatin resistance in human lung cancer cell lines via the transforming growth factor-β/Smad2/STAT3/STAT5 pathway." (PMID 26317552, 2015). "Mechanistically, TMED10 may exert tumor-promoting effects via disruption of TGF-β receptor complex formation, as observed in lung cancer models, where it attenuates Smad2 activation and downstream TGF-β signaling pathways." (PMID 40826138, 2025). "LINC01132 may regulate the progression of lung cancer by targeting the miR-125a-3p /SMAD2 axis and serve as a prognostic biomarker for lung cancer." (PMID 38403680, 2024). "TGF-β/SMAD2 genes are considered the markers of A549 Lung cancer cells." (PMID 39347291, 2024). "In the present study, the activation of the Smad2/3 and Src/MAPK pathways follows the same trend with the up-regulation of GRP78; moreover, knockdown of GRP78 inhibited the activation of Smad2/3 and Src, suggesting a causal link between GRP78 and activation of the two pathways in lung cancer." (PMID 30931255, 2019). "Our study aims to evaluate whether the nickel-induced oxidative damage and DNA repair were correlated with the alterations in Smad2 phosphorylation status and Nkx2.1 expression levels, which has been considered as the lung cancer initiation gene." (PMID 30621196, 2019). "Furthermore, we also observed that EP treatment resulted in the reduced protein expression of Smad2 and Smad3, which are important for lung cancer growth and metastasis." (PMID 30560887, 2018). "Additionally, the activation of the Smad2/3 and Src/MAPK pathways, associated with GRP78 signaling in lung cancer, suggests that the knockdown of GRP78 inhibits the activation of Smad2/3 and Src, indicating a causal relationship between GRP78 and these pathways." (PMID 38921583, 2024).
lung cancer (continued). "Specifically, TGF-β can trigger the classic TGF-β/Smad signaling pathway by intensifying Smad2/3 phosphorylation, thereby igniting the EMT process in various malignancies such as esophageal, gastric, and lung cancers." (PMID 37872157, 2023). "In Lewis lung cancer cells, the overexpression of LRG1 has been found to enhance the SMAD2 signaling pathway, which is also activated by TGF-β1." (PMID 37569820, 2023). "In lung cancer, profiling-2 and ACP5 regulate Smad2 and Smad3 expression for lung cancer growth and metastasis, and miR-15a and miR-32-5p directly regulate SMAD3 expression for lung cancer metastasis." (PMID 37121971, 2023). "Here we demonstrate that circ-0001875, identified as a novel circRNA upregulated in lung cancer, regulates the miR-31-5p/SP1 axis with an oncogenic role to promote EMT via a TGFβ/Smad2 signal pathway." (PMID 35473752, 2022). "Expression of PFN2 induced the transactivation of Smad2 and Smad3, and these transmission factors enhanced TGF-β-induced EMT and angiogenesis in lung cancer." (PMID 35327465, 2022). "We provide the first evidence that JMJD3 epigenetically regulates the expression levels of syntenin via H3K27me3 demethylation, leading to TGF-β1-induced Smad2/3 activation and EMT in lung cancer cells." (PMID 33637682, 2021). "Further studies found that SETDB1 functionally cooperated with the TGFb-regulated complex SMAD2/3 to inhibit the expression of Annexin A2 (ANXA2), which plays a crucial role in lung cancer metastasis." (PMID 34299035, 2021). "EGFRex19 and KRASG12C cancer cell clusters displayed differential enrichment in lung cancer signatures, proliferation signatures, epithelium development, and TGF-β signaling through SMAD2 and SMAD3, when compared to other epithelial clusters." (PMID 33712615, 2021). "Here, we demonstrated that JMJD3 histone H3K27 demethylase plays an important role in the collaboration between TGF-β signaling and oncogenic RAS for activation of Smad2/3 and EMT in human lung cancer cells." (PMID 33637682, 2021). "One paper reported that miR-27a upregulated in lung cancer cell lines and patients and impaired TGF-β signaling by inhibiting Smad2 and Smad4, and its overexpression decreased Smad2 and Smad4 mRNA and protein levels." (PMID 34712379, 2021). "So, Yiqi Chutan Recipe (YCR, a Chinese herbal prescription) was found to inhibit or even reverse hypoxia-stimulated EMT in lung cancer A549 cells through the inhibition of GRP78 expression along with downregulation of Src, MAPK, and Smad2/3." (PMID 32268506, 2020). "In A549 lung cancer cells, EGCG treatment determined TGFβ1-mediated EMT inhibition by suppressing the acetylation of Smad2 and Smad3." (PMID 31480720, 2019). "In human lung cancer cells, EGCG inhibits TGF-β1-mediated EMT by suppressing the acetylation of Smad2 and Smad3." (PMID 31311401, 2019). "TGF-β2 signals through TGFBR1, TGFBR2, SMAD2, and SMAD4 to upregulate WNT7B mRNA expression in lung cancer cells." (PMID 30971692, 2019). "Taken together, these data showed that fucoidan inhibition of cell viability in lung cancer cells partly involves targeting TGFR, with the consequent attenuation of the Smad2/3, Akt, and Erk signaling pathways." (PMID 25149540, 2014). "For example, SMAD2 activated by TGF-β signaling upregulates the expression of EPHB1, which further promotes epithelial–mesenchymal transition (EMT) by elevating CDH2 expression in lung cancer." (PMID 40548257, 2025). "The introduction of silencing SMAD2 reversed the effect of miR-125a-3p inhibitor on the biological activity of lung cancer cells, suggesting that LINC01132 may participate in the progression of lung cancer by mediating the miR-125a-3p/SMAD2 axis." (PMID 38403680, 2024). "To model the SMAD2/3 differences observed in TAFs, we stably knocked down SMAD2 or SMAD3 by shRNA in control fibroblasts derived from uninvolved pulmonary tissue of a randomly selected surgical lung cancer patient (#5)." (PMID 36572730, 2023).
lung cancer (continued). "Moreover, a different study on lung cancer has reported the concurrent upregulation of miR-27a and downregulation of two significant mediators of the TGF-β signaling pathway, SMAD2, and SMAD423." (PMID 36344812, 2022). "Importantly, restoration of KDM4C partially rescued the reduced levels of TGF-β2, p-Smad2 and p-Smad3 in USP9X-depleted lung cancer cells, suggesting that USP9X silencing inhibits TGF-β2/Smad signaling in a KDM4C-dependent manner." (PMID 33558705, 2021). "Another regulation of Smad2/3 proteins showed that profilin-2 interacts with HDAC1 to inhibit the binding of HDAC1 to the promoters of Smad2 and Smad3, leading to their activation and enhancing the TGF-β-induced EMT and angiogenesis in lung cancer cells." (PMID 32114978, 2020). "Furthermore, we found the alteration of Snail levels by modulating GPR81 expression or inhibition of MCT1 was correlated with changes in phosphorylation of SMAD2/3, indicating Snail induces EMT of lung cancers as a downstream of TGF-β1/SMAD canonical pathway." (PMID 29482580, 2018). "TGF-β-induced CD59 expression during EMT is dependent on Smad3 but not on Smad2 in lung cancer A549 cells." (PMID 27548154, 2016). "Importantly, SMASR inhibits the TGFβRI by interacting with Smad2/3, leading to the inactivation of the TGFβ/SMAD signaling pathway and forming a negative feedback loop, which plays a critical role in regulating EMT in lung cancer." (PMID 39083441, 2025). "Glabridin inhibits cancer stem cell formation via the TGF-β/SMAD2 pathway in breast and liver cancers, and epithelial–mesenchymal transition through upregulation of E-cadherin and cancer cell migration and invasion by blocking FAK/Src activation in breast and lung cancers." (PMID 41470858, 2025). "MSCs-derived exosomes promote EMT, invasion and migration of lung cancer cells, while silencing the expression of TGF-β1 in MSCs may inhibit MSCs-derived exosomes-mediated EMT formation of lung cancer by inactivating Smad2/3, Akt/GSK-3β/β-catenin, NF- κB, ERK, JNK and p38MAPK signaling pathways." (PMID 39679363, 2024). "However, our knowledge of how SMAD2/3 control cell migration is very limited, and their impact on the formation of the desmoplastic TME in lung cancer is unknown." (PMID 36572730, 2023). "Therefore repressing Smad2, Smad3, and Smad4 nuclear translocation may regulate EMT-related TGF-β and suppress metastasis and tumor growth in lung cancer." (PMID 32405368, 2020). "High mobility group protein A2 (HMGA2) has been shown to promote lung cancer progression in mouse and human cells by competing with TGF-β type III receptor for the let-7 microRNA (miRNA) family, while decreased let-7g levels influence the TGF-β pathway by targeting TβR1 and SMAD2 gene expression." (PMID 31195692, 2019). "In addition, there is especially a lack of evidence about the prognostic significance of Smad2 expression in stromal fibroblasts of lung cancer." (PMID 25373709, 2014). "To further clarify the role of USP9X in lung cancer radioresistance and confirm whether this effect is dependent on KDM4C, we transfected exogenously expressed KDM4C into USP9X-depleted cells and found that TGF-β2, p-Smad2 and p-Smad3 protein levels were decreased when USP9X was knocked down." (PMID 33558705, 2021). "However, not much is known regarding the prognostic value of Smad2 expression in lung cancer cells." (PMID 25373709, 2014). "Interestingly, in the same study, lung cancer patients had no increase in myostatin serum levels but did have increases in Smad2 expression, raising the question whether different tumors might induce different patterns of molecular changes within skeletal muscle tissue." (PMID 26856534, 2016). "The silencing of HSP27 enhances an additive effect with TGF-β1-induced EMT and the TGF-β1-induced HSP27 increase is not affected by the suppression of Smad2 and Smad3 in A549 cells, which suggests that HSP27 is involved in TGF-β1-induced EMT in a Smad-independent manner in lung cancer cells." (PMID 29062135, 2017).
pancreatic cancer (75 papers, 2008 to 2025). "In the next study, we will focus on the mechanism of TGF-β1 and SMAD2/3 regulating the PNI of pancreatic cancer and the underlying mechanisms need further exploration." (PMID 34671554, 2021). "For example, Smad2 and Smad3 mutations have been found in colon cancer, pancreatic cancer, and other tumors." (PMID 34489426, 2021). "Pancreatic cancer has detected loss of function or truncating mutations of TGFβRI, TGFβRII, Smad2, and Smad4 genes." (PMID 28794854, 2017). "These SMAD2-deficient stable PANC-1 cells were injected into a murine orthotopic pancreatic cancer model." (PMID 29018205, 2017). "Somatic ACVR1B gene mutations have been found in pancreatic carcinoma and Smad2 and Smad4 are mutated in colorectal and pancreatic carcinomas." (PMID 19538713, 2009). "Smad4 deficient pancreatic carcinoma cell lines express increased levels of phosphorylated Smad2 (P-Smad2)." (PMID 19849841, 2009). "Indeed, pancreatic cancer progression requires shutting down the tumor-suppressive effects of TGF-β signaling through mutation Smad transcription factors (Smad2, Smad4)." (PMID 28794854, 2017). "Furthermore, missense mutations in the Smad2 and Smad4 genes occurring in colon and pancreatic cancer cells, respectively, have been reported to inhibit association of Smad2 with Smad4." (PMID 24386222, 2013). "While reducing ALK4 expression did not consistently alter activin A- or Nodal-induced Smad2/3 phosphorylation, it significantly enhanced TGF-β1-mediated Smad2/3 phosphorylation in both breast and pancreatic cancer models." (PMID 41408046, 2025). "In conclusion, we found that the EMP1-promoted binding of VASP and SMAD7 in pancreatic cancer promotes the activation of the TGF-β/Smads signaling pathway characterized by enhanced phosphorylation of SMAD2/3." (PMID 41285728, 2025). "Treatment with atorvastatin or NSDHL knockout activates SREBP1, which promotes TGF-β1 expression and induces a canonical Smad2 and Smad3 effector cascade, resulting in the induction of epithelial-mesenchymal transition in pancreatic cancer." (PMID 39516821, 2024). "For example, ITGA2 inhibits the activation of the TGF-β pathway through transcriptional repression of SMAD2 expression, which in turn promotes the growth of pancreatic cancer cells." (PMID 37685308, 2023). "Honokiol inhibits the invasive migration and perineural invasion of pancreatic cancer by inhibiting the phosphorylation of SMAD2/3, reducing the tumour cell damage to the sciatic nerve and protecting sciatic nerve function." (PMID 37685308, 2023). "Taken together, these findings indicated that the ITGA2 silencing induced the SMAD2 expression in pancreatic cancer cells." (PMID 35193647, 2022). "The LINC00462 promotes pancreatic cancer invasiveness through the miR-665/TGFBR1-TGFBR2/SMAD2/3 pathway." (PMID 36104680, 2022). "Our findings are consistent with a previous article reporting that ITGA5 induces tumor cell proliferation and migration in pancreatic cancer through the activation of the FAK/Smad2 pathway." (PMID 36193075, 2022). "Meanwhile, the protein expression levels of SMAD2, SMAD3, SMAD4, and p-SMAD2/3 were also detected in the pancreatic cancer cells with the ITGA2 gene silenced." (PMID 35193647, 2022). "Taken together, these findings indicated that TFCP2 induced the SMAD2 expression by acting as a transcription factor in the pancreatic cancer cells." (PMID 35193647, 2022). "Macrophages promote endothelial-to-mesenchymal transition via MT1-MMP/TGF-β1 after myocardial infarction, and CD51+ macrophages promote cancer stem cell properties through the TGF-β1/Smad2/3 axis in pancreatic cancer." (PMID 35587159, 2022). "Searching the GEPIA database showed that the mRNA expression levels of TFCP2 were positively correlated with those of the SMAD2 in pancreatic cancer cells." (PMID 35193647, 2022). "The overexpression of LINC00462 improved TGFBR1 and TGFBR2 expression levels to activate the SMAD2/3 signaling pathway in pancreatic cancer." (PMID 33622186, 2021).